MIR3685 (microRNA 3685)
Synonyms: hsa-mir-3685
Gene: MicroRNA gene on chromosome 12 (95,309,923 to 95,309,984, forward strand). Ensembl gene ENSG00000265917.
Homologues: Orthologues: chimpanzee MIR3685 (100% identical).